TCF25 (TCF25 ribosome quality control complex subunit)
Description:
Component of the ribosome quality control complex (RQC), a ribosome-associated complex that mediates ubiquitination and extraction of incompletely synthesized nascent chains for proteasomal degradation. In the RQC complex, required to promote formation of 'Lys-48'-linked polyubiquitin chains during ubiquitination of incompletely synthesized proteins by LTN1. May negatively regulate the calcineurin-NFAT signaling cascade by suppressing the activity of transcription factor NFATC4 (By similarity). May play a role in cell death control (By similarity).
Synonyms: KIAA1049; NULP1; FKSG26; Hulp1; PRO2620; hKIAA1049
Tractability: PROTAC: ubiquitination databases record sites on it; its protein half-life has been measured.
Gene: Protein-coding gene on chromosome 16 (89,873,566 to 89,913,627, forward strand). Ensembl gene ENSG00000141002.
Subcellular location: Nucleus; Cytoplasm, cytosol
Pathways (Reactome):
Metabolism of proteins: Ribosome Quality Control (RQC) complex extracts and degrades nascent peptide
Gene Ontology:
Molecular function: protein binding
Biological process: regulation of protein K48-linked ubiquitination; rescue of stalled ribosome; ribosome-associated ubiquitin-dependent protein catabolic process
Cellular component: nucleus; RQC complex; cytosol
Genetic constraint (gnomAD): Loss-of-function variants: 41 observed, 79.12 expected, observed/expected ratio (o/e) 0.52, 90% interval 0.4 to 0.67. The synonymous counts are far from expectation, so gnomAD's model fits this gene poorly and the ratio says little. Missense variants: 979 observed, 922.04 expected, observed/expected ratio (o/e) 1.06, 90% interval 1.01 to 1.12. Synonymous variants: 458 observed, 367.7 expected, observed/expected ratio (o/e) 1.25, 90% interval 1.15 to 1.35.
Homologues: Orthologues: chimpanzee TCF25 (94% identical), mouse Tcf25 (90% identical), rat Tcf25 (90% identical), guinea pig TCF25 (88% identical), macaque TCF25 (87% identical), rabbit TCF25 (85% identical), dog TCF25 (79% identical), tropical clawed frog tcf25 (58% identical), zebrafish tcf25 (55% identical), Drosophila melanogaster Nulp1 (37% identical), Caenorhabditis elegans K07A12.1 (25% identical).
Diseases named in the same sentence as TCF25 in open-access papers:
TCF25 is named in the same sentence as 16 diseases in open-access papers, as found by Europe PMC text mining. Sharing a sentence is not in itself a finding about the gene and the disease. The quoted sentences say what the papers report.
bladder cancer (5 papers, 2018 to 2023). "A similar mechanistic mode has been proposed in bladder carcinoma where circular RNA TCF25 serves as a molecular sponge for miR-107 to upregulate CDK6 expression and promote proliferation." (PMID 37744274, 2023). "MiR103A-3p also participates in circRNA Dicer1-mediated glioma endothelial cell migration and circRNA TCF25 regulated the invasion and migration of bladder cancer cells." (PMID 34787047, 2021). "In addition, circ-TCF25 regulates the proliferation, migration, and invasion of bladder cancer cells via miR-103a-3p/miR-107-CDK6 pathway." (PMID 30621721, 2019).
hearing loss (2 papers, 2024 to 2025). "CpG cites in hearing loss candidate genes, KCNQ1, TMEM43, GSTM1, TCF25, and GSR, were found to be highly methylated in presbycusis patients as compared to the controls." (PMID 40428348, 2025).
Obesity (2 papers, 2021). Accumulation of substantial excess body fat. "On the other hand, genes up-regulated with pregravid obesity enriched to GO terms associated with transcriptional regulation (JMJD1C, CHD1, HIF1A, TCF25, and KLF6)." (PMID 33912153, 2021). "An even more pronounced reduction was observed for Eif5, whereas expression of Tcf25 and Bin1 were not altered by diet-induced obesity." (PMID 33257475, 2021).
cardiac hypertrophy (1 paper, 2025). "Mammalian NULP1, also known as TCF25, acts as a suppressor of NFAT3-mediated transcriptional activity in cardiac hypertrophy, independently of calcineurin." (PMID 41210950, 2025).
malaria (1 paper, 2025). Malaria is a serious and sometimes fatal disease caused by a parasite that commonly infects a certain type of mosquito which feeds on humans. "These forthcoming research endeavors not only aim to refine our understanding of TCF25’s diverse functions but also hold the promise of unveiling novel facets of translational regulation in malaria parasites." (PMID 41210950, 2025). "In conclusion, our comprehensive multi-omics analysis has unveiled novel functions of TCF25 in the regulation of malaria parasite transmission and gene expression, shedding new light on gametocytogenesis and ribosome biogenesis in P. falciparum." (PMID 41210950, 2025). "This discovery highlights TCF25 as a previously unrecognized regulatory factor in the sexual development pathway, enhancing our understanding of the mechanisms involved in this crucial biological transition essential for malaria transmission." (PMID 41210950, 2025).
cancer (3 papers, 2013 to 2018). A tumor composed of atypical neoplastic, often pleomorphic cells that invade other tissues. "ELOVL7, PTDSS1, POLR1D, TBC1D22A, CCNC and TCF25 are some of the interesting genes with cancer related functions identified from the DES analysis." (PMID 24088394, 2013). "In fact, TCF25, has been involved in embryonic development expressed in brain, and KLF3, has been reported to show rearrangements in different cancer types." (PMID 24884915, 2014).
TCF25 also shares sentences with these, for which no sentence is quoted: anemia (1 paper); gastric cancer (1); glioma (1); hepatocellular carcinoma (1); lung carcinoma (1); otosclerosis (1); presbycusis (1); schizophrenia (1); tumor (1); type 2 diabetes mellitus (1).